LRP1B (LDL receptor related protein 1B)
Diseases named in the same sentence as LRP1B in open-access papers (continued):
Sharing a sentence is not in itself a finding about the gene and the disease.
Obesity (6 papers, 2010 to 2024). Accumulation of substantial excess body fat. "One such locus in Chileans displays significant allele frequency differentiation within the Low-density lipoprotein Receptor Related Protein 1B (LRP1B) gene, previously linked to obesity, a known CRC risk factor." (PMID 38731914, 2024). "We performed the genetic and epigenetic association study of LRP1B gene with obesity-related traits, as well as the sequence dependent methylation patterns linked to childhood obesity." (PMID 30755693, 2019). "Here, we investigated the genetic polymorphisms of LRP1B in obesity by exome sequencing in a childhood obesity sample." (PMID 30755693, 2019). "Previous genetic association studies of the LRP1B gene have shown its genetic association with obesity." (PMID 30755693, 2019). "Genetic association studies of novel obesity-related gene variants in large populations have reported LRP1B as a factor in obesity susceptibility." (PMID 30755693, 2019). "The genetic influences of obesity on the LRP1B gene may be linked to the interplay of CpG methylations in the same intron." (PMID 30755693, 2019). "Through exome sequencing of the LRP1B gene from a childhood severe obesity cohort (n = 692), we found novel single nucleotide polymorphism (rs431809) in intron 4, which has been significantly correlated with both body mass index (BMI) and waist-hip-ratio (WHR)." (PMID 30755693, 2019). "Therefore, further analysis of obesity-related differential methylation region and genetic variations of LRP1B, may explain where and how sophisticated epigenetic regulations changes come from." (PMID 30755693, 2019).
renal cell carcinoma (6 papers, 2015 to 2024). "Silencing and down-regulation of LRP1B are found in various cancers, including renal cell carcinoma, and only low levels of LRP1B transcripts were observed here." (PMID 38898085, 2024). "In renal cell cancer, down-regulation of LRP1B has been shown to regulate cell motility and actin cytoskeleton reorganization." (PMID 27047539, 2016).
dementia (5 papers, 2010 to 2025). Loss of intellectual abilities interfering with an individual's social and occupational functions. "TRPM3 has been related to neurodevelopmental disorders concerning speech/language skills and mild-to-severe intellectual disability, while the LRP1B gene was found to be a major risk factor in the progression to Parkinson’s disease dementia." (PMID 38791296, 2024). "Connecting to Alzheimer’s disease, dementia, and amyloidosis hubs include prominent AD-associated proteins such as the low-density lipoprotein receptor-related proteins LRP1, LRP1B, LRP4, and LRP6." (PMID 33946285, 2021). "Furthermore, LDL receptor related protein 1B (LRP1B, 2q22.2) is a member of low‐density lipoprotein (LDL) receptor family and a key regulator of tau spread and aggregation in dementia." (PMID 40631452, 2025).
Alzheimer disease (4 papers, 2012 to 2023). A progressive, neurodegenerative disease characterized by loss of function and death of nerve cells in several areas of the brain leading to loss of cognitive function such as memory and language. "Ultimately, three proteins associated with Alzheimer’s disease were selected: 14-3-3 protein zeta/delta, low-density lipoprotein-receptor-related protein 1B (LRP1B), and calreticulin." (PMID 37630190, 2023). "The LRP1B C/C genotype has been associated with a higher risk of Alzheimer’s disease." (PMID 37630190, 2023). "LRP1B also plays a role in removing β-amyloid across the blood–brain barrier, and its reduced or absent expression may result in decreased clearance of β-amyloid and ApoE/α2-macroglobulin complexes, thereby increasing the risk of Alzheimer’s disease." (PMID 37630190, 2023). "LRP1B was recently identified as an essential mediator of C1q-induced protection against β-amyloid neurotoxicity in Alzheimer’s disease mouse models, which partly explains how ACE inhibitors reduce β-amyloid-dependent neurodegeneration." (PMID 37630190, 2023).
atherosclerosis (4 papers, 2012 to 2025). A disease characterized by the build-up of fatty material and calcium deposition in the arterial wall resulting in partial or complete occlusion of the arterial lumen. "Most of the recently identified ligandsof LRP1B are well-known factors of blood coagulation and oflipoprotein metabolism, suggesting that LRP1B is implicatedin atherosclerosis." (PMID 37808210, 2023). "Based on the normal lipid profiles identified in both the control and CAD groups, we conclude that increased LRP1B expression is associated with blood cholesterol levels but is not a direct indicator of atherosclerosis." (PMID 39445733, 2025). "Together, these studies suggest that LRP1B may play a role in atherosclerosis development." (PMID 39445733, 2025). "The LRP2BP and LRP1B genes are two members of the low-density lipoprotein receptor family that participates in a wide range of physiological processes, including the regulation of lipid metabolism, protection against atherosclerosis, neurodevelopment, and transport of nutrients and vitamins." (PMID 23241142, 2012).
bladder cancer (4 papers, 2021 to 2024). "Somatic mutations of LRP1B are estimated to occur in 12% of all human cancer cases, and in more than 20% of cases of certain tumor types, including bladder cancers." (PMID 37079639, 2023). "Comparison of “predictive” CNAs and CSCs data revealed that LRP1B loss was also significantly more represented in CSCs, confirming its prominent role in bladder cancer." (PMID 35841413, 2022). "Sporadic missense mutations of LRP1B have been reported previously in canine bladder cancers." (PMID 37079639, 2023). "LRP1B loss was significantly increased in CSCs and linked to short-term poor prognosis, both at genomic and transcriptomic level, confirming its pivotal role in bladder cancer tumorigenesis." (PMID 35841413, 2022). "LRP1B loss was significantly increased in CSCs and for the first time linked to short-term prognosis (1-year survival), both at genomic and transcriptomic level, confirming its pivotal role in bladder cancer tumorigenesis." (PMID 35841413, 2022). "LRP1B role as a candidate tumor suppressor also for bladder cancer has been proposed several years ago; however, its function still remains to be fully elucidated." (PMID 35841413, 2022).
cutaneous melanoma (4 papers, 2022 to 2025). A primary melanoma arising from atypical melanocytes in the skin. "The results suggested that LRP1B displayed a high mutation frequency in skin cutaneous melanoma (37.55%), LUAD (30.08%), LUSC (29.24%), and stomach adenocarcinoma (23.67%); this was consistent with the results obtained from the cBioPortal database." (PMID 36204371, 2022). "In Thy-AdenoCA, the genes NRXN3 and LRP1B exceeded this threshold, as well as PCDH15 in Eso-AdenoCA and Skin-Melanoma." (PMID 40507213, 2025). "Among them, PKHD1L1, LRP1B, ADGRV1 and DNAH10 were hypomethylated in UV-mutant compared with non UV-mutant cutaneous melanoma patients in BCH." (PMID 35840550, 2022).
esophageal squamous cell carcinoma (4 papers, 2019 to 2025). Esophageal squamous cell carcinoma (ESCC) is a type of esophageal carcinoma (EC) that can affect any part of the esophagus, but is usually located in the upper or middle third. "Annotated as a tumor suppressor in the COSMIC database, LRP1B is also frequently mutated in chronic lymphatic leukemia, esophageal squamous cell carcinoma, ovarian, and urothelial cancers." (PMID 41153425, 2025).
squamous cell carcinoma (4 papers, 2021 to 2024). A carcinoma arising from squamous epithelial cells. "It was found that in 2,616 coding genes, 2 or more integration sites presented among samples, like RAD51B, MACROD2, FHIT, CSMD1, LRP1B, and DLG2, which had already been previously reported as frequent sites of integration in squamous carcinoma samples." (PMID 33810183, 2021).
diabetes mellitus (3 papers, 2010 to 2025). A metabolic disorder characterized by abnormally high blood sugar levels due to diminished production of insulin or insulin resistance/desensitization. "Recently, LRP1B single nucleotide polymorphism (rs10496915, rs431809, and rs6742944) were assessed in OSCC patients with diabetes mellitus." (PMID 40457841, 2025). "The purpose of the current study was to investigate how low-density lipoprotein receptor-related protein 1B (LDL receptor related protein 1B; LRP1B) gene polymorphisms affect oral squamous cell carcinoma (OSCC) risk and progression in individuals with diabetes mellitus (DM)." (PMID 38612772, 2024).
glioma (3 papers, 2023 to 2025). A benign or malignant brain and spinal cord tumor that arises from glial cells (astrocytes, oligodendrocytes, ependymal cells). "Research indicates a strong link between LRP1B deletion and the development of glioma, particularly in patients with wildtype IDH1/2." (PMID 40564017, 2025). "Moreover, fusion between two exons was observed in glioma cell lines, resulting in premature termination codon appearance, and overexpression of miR‐548a‐5p and miR‐301b‐3p leading to the downregulation of LRP1B." (PMID 39660409, 2024).
heart failure (3 papers, 2017 to 2023). Inability of the heart to pump blood at an adequate rate to meet tissue metabolic requirements. "However, the LRP1B gene is located on 2q22.1, a genomic region previously implicated in premature coronary atherosclerotic disease and heart failure." (PMID 38002962, 2023). "Association was also detected within LRP1B, a LDL receptor gene, located on 2q22.1, a genomic region previously implicated in CHD and heart failure." (PMID 29221444, 2017). "Moreover, a nearby gene, LRP1B, a member of the LDL receptor gene family, has previously been implicated in CHD and heart failure." (PMID 33374401, 2020).
Insulin resistance (3 papers, 2014 to 2020). Increased resistance towards insulin, that is, diminished effectiveness of insulin in reducing blood glucose levels. "LRP1B gene polymorphism was associated with insulin resistance, uncontrolled emotional eating, and childhood BMI." (PMID 32337289, 2020). "The LRP1B gene has also been associated with insulin resistance and tumor suppression in humans and LDL cholesterol levels in rats." (PMID 29221444, 2017). "Furthermore, polymorphisms in the LRP1B gene were found to be associated with insulin resistance and preeclampsia in human studies." (PMID 25296178, 2014).
lymph node metastasis (3 papers, 2021 to 2025). "In particular, patients with mutations in the LRP1B gene had a lower probability of lymph node metastasis." (PMID 40778224, 2025). "Multiple‐variate Cox proportional hazards regression analysis further revealed that N stage (HR = 3.151, 95% CI = 1.307–7.594, p = 0.011) was an independent risk factor for OS in the LRP1B group, indicating that a low LRP1B expression status promotes lymph node metastasis in patients with EJA." (PMID 34152098, 2021). "CDK6, MET, NOTCH1, and LRP1B mutation frequencies showed significant differences in cases with (N ≥ 1) or without (N = 0) lymph node metastasis." (PMID 34152098, 2021). "In this study, we found that LRP1B was underexpressed in EJA tissues with lymph node metastasis and that a high LRP1B expression status may inhibit lymph node metastasis and predict a favorable prognosis." (PMID 34152098, 2021). "Specifically, the mutation frequencies of CDK6, MET, and NOTCH1 noticeably lower in cases with stage N0 than in those with stage N ≥ 1, whereas LRP1B mutation frequency was remarkably higher in cases without lymph node metastasis." (PMID 34152098, 2021). "In this study, we demonstrated that a high CDK6 expression status may promote lymph node metastasis and that a high LRP1B expression status inhibits lymph node metastasis in patients with EJA." (PMID 34152098, 2021). "tNGS revealed that CDK6 and LRP1B mutation frequencies were significantly different between EJA cases with (N ≥ 1) or without (N = 0) lymph node metastasis." (PMID 34152098, 2021). "A high CDK6 expression status may promote lymph node metastasis, while a high LRP1B expression status may inhibit lymph node metastasis." (PMID 34152098, 2021). "Together, our findings indicate that CDK6 and LRP1B have significant potential as indicators of prognosis and lymph node metastasis in patients with EJA and could be targeted for molecular targeted therapy." (PMID 34152098, 2021). "This indicates that intact LRP1B may be essential for the process of lymph node metastasis in LSCC." (PMID 40778224, 2025).
metastasis (3 papers, 2021 to 2025). The spread or migration of cancer cells from one part of the body (where they first appeared) to another. "Supporting this hypothesis, the expression level of LRP1B was significantly higher in the lymphatic metastasis group compared to the group without lymphatic metastasis, and a similar trend has also been observed in esophagogastric junction adenocarcinoma." (PMID 40778224, 2025).
oral cancer (3 papers, 2012 to 2025). "We further analyzed the risk association of LRP1B rs6742944 for tongue and buccal mucosa cancers among DM cohorts with oral cancer." (PMID 38612772, 2024). "We also looked at the relationship between oral cancer susceptibility and LRP1B genotypic frequencies." (PMID 38612772, 2024). "This is the first study to show how DM and LRP1B gene polymorphisms interact to influence the development of oral cancer." (PMID 38612772, 2024). "Between the case and control groups, there was no discernible relationship found between these LRP1B polymorphisms and the likelihood of developing oral cancer." (PMID 38612772, 2024).
adenoid cystic carcinoma (2 papers, 2015 to 2020). A malignant tumor arising from the epithelial cells. "Among other salivary gland neoplasms, genomic alterations in FBXW7, KLHL6, and LRP1B have been identified in adenoid cystic carcinoma." (PMID 26634163, 2015). "A few other factors, such as presence of specific tumor histologies (adenoid cystic carcinoma and non-medullary thyroid carcinoma; favorable), and presence of LRP1B mutation (unfavorable), retained their respective associations with survival." (PMID 32110280, 2020).
B-cell lymphoma (2 papers, 2021 to 2024). "However, several associations have not yet been reported, including overexpression of WNK2 in high-grade B-cell lymphoma, of FAT4 in multiple myeloma, and of LRP1B in hairy cell leukemia (HCL), hairy cell leukemia variant (HCL-V), and marginal zone lymphoma (MZL)." (PMID 38769532, 2024).
brain cancer (2 papers, 2017 to 2022). A primary or metastatic malignant neoplasm affecting the brain. "Many of these genes were associated with several cancer types, for example LRP1B has been associated with thyroid, ovarian, renal, and brain cancers." (PMID 28359308, 2017). "From our primary analysis of the TPMI dataset for the Han population, LRP1B mutation showed more significant expression in benign neoplasms than in malignant neoplasms of the brain, suggesting that LRP1B acts as a tumor-suppressor gene (TSG) in benign brain tumors." (PMID 35887658, 2022). "Both LRP1B and FRMD3 serve as TSGs in brain tumors, and some research has shown that LRP1B deletion affects the prognosis of malignant brain neoplasms, including GBM and medulloblastoma, in the U.S. population according to TCGA data." (PMID 35887658, 2022). "Other SNP profiles revealed different molecules, including DDP6, NDUFB9, EDARADD, EST1, MC4R, LRP1B, and FRMD3, which perform different roles in brain neoplasms or malignancies." (PMID 35887658, 2022). "LRP1B enhances expression of CD133, a cancer stem cell marker of brain neoplasms, to affect serum-starved medulloblastoma." (PMID 35887658, 2022).
chronic obstructive pulmonary disease (2 papers, 2020 to 2021). A chronic and progressive lung disorder characterized by the loss of elasticity of the bronchial tree and the air sacs, destruction of the air sacs wall, thickening of the bronchial wall, and mucous accumulation in the bronchial tree. "A previous study of LUAD patients with chronic obstructive pulmonary disease had revealed the prevalence of LRP1B mutations in male patients." (PMID 33488709, 2020).
Cognitive impairment (2 papers, 2012 to 2024). Abnormal cognition is characterized by deficits in thinking, reasoning, or remembering. "If LRP1B is haploinsufficient in our patient, and considering its biological function within the central nervous system, it is tempting to speculate on the participation of this gene in the patient’s observed cognitive impairment." (PMID 22686481, 2012).
head and neck squamous cell carcinoma (2 papers, 2021 to 2025). A squamous cell carcinoma that arises from any of the following anatomic sites: lip and oral cavity, nasal cavity, paranasal sinuses, pharynx, larynx, and salivary glands. "Several reports have shown the occurrence of LRP1B mutation in cell lines of tongue cancer and head and neck squamous cell carcinoma (HNSCC)." (PMID 40457841, 2025).
meningioma (2 papers, 2017 to 2020). A generally slow growing tumor attached to the dura mater. "Other than NF2, the most frequently mutated genes were CDC27 and LRP1B, mutated in 10 (9%) and 9 (8%) samples, respectively, of the total set of 115 meningiomas." (PMID 28713588, 2017).
metastatic melanoma (2 papers, 2019). A melanoma that has spread from its primary site to another anatomic site. "For example, metastatic melanomas bearing mutations in LRP1B gene have a significantly higher mutational load as compared with LRP1B wild type tumors; furthermore, mutational load correlates with the number of LRP1B mutations per tumor." (PMID 31406485, 2019).
neuroblastoma (2 papers, 2023 to 2025). Neuroblastoma (NB) is the most common solid, extracranial childhood tumor. "Two types of angiotensin-converting enzyme (ACE) inhibitors, lisinopril and benazepril HCl, were tested in neuroblastoma cells and found to upregulate low-density lipoprotein-receptor-related protein 1B (LRP1B) and 14-3-3 protein zeta/delta." (PMID 37630190, 2023). "We observed that both ABCA13 and LRP1B are expressed at higher levels in MYCN non-amplified neuroblastoma, a subgroup typically associated with less heterogeneous outcomes." (PMID 40599792, 2025). "Notably, our findings suggest a potential mechanistic link between LRP1B mutation and WNT signaling activation in neuroblastoma." (PMID 40599792, 2025).
acute lymphoblastic leukemia (1 paper, 2019). Leukemia with an acute onset, characterized by the presence of lymphoblasts in the bone marrow and the peripheral blood. "Epigenetic regulation of LRP1B results in changes to the tumor environment, such as the aberrant methylation of LRP1B in acute lymphoblastic leukemia and in gastric cancer." (PMID 30755693, 2019).